PRSS16 (serine protease 16)
Description:
Protease that may play a role in T-cell development.
Synonyms: TSSP
Tractability: Antibody: UniProt predicts a signal peptide or a membrane-spanning region.
Gene: Protein-coding gene on chromosome 6 (27,247,701 to 27,256,646, forward strand). Ensembl gene ENSG00000112812.
Subcellular location: Cytoplasmic vesicle
Gene Ontology:
Molecular function: serine-type peptidase activity; serine-type exopeptidase activity
Biological process: protein catabolic process; proteolysis
Cellular component: endosome; lysosome; cytoplasmic vesicle
Genetic constraint (gnomAD): Loss-of-function variants: 44 observed, 60.21 expected, observed/expected ratio (o/e) 0.73, 90% interval 0.57 to 0.94. The upper end of that interval is the gene's LOEUF score, 0.94, which puts it in group 3 of 6, group 1 being the genes least tolerant of losing a copy. Missense variants: 589 observed, 667.7 expected, observed/expected ratio (o/e) 0.88, 90% interval 0.82 to 0.94. Synonymous variants: 273 observed, 286.24 expected, observed/expected ratio (o/e) 0.95, 90% interval 0.86 to 1.05.
Homologues: Orthologues: chimpanzee PRSS16 (99% identical), macaque PRSS16 (96% identical), pig PRSS16 (82% identical), mouse Prss16 (79% identical), rabbit PRSS16 (78% identical), rat Prss16 (77% identical), guinea pig PRSS16 (59% identical), tropical clawed frog prss16 (43% identical), Caenorhabditis elegans pcp-2 (28% identical), Caenorhabditis elegans pcp-3 (27% identical), Caenorhabditis elegans pcp-4 (25% identical), Caenorhabditis elegans F19C7.2 (25% identical), and 5 more. Paralogues in human: DPP7 (26% identical), PRCP (24% identical).
Diseases named in the same sentence as PRSS16 in open-access papers:
PRSS16 is named in the same sentence as 19 diseases in open-access papers, as found by Europe PMC text mining. Sharing a sentence is not in itself a finding about the gene and the disease. The quoted sentences say what the papers report.
schizophrenia (3 papers, 2012 to 2025). A major psychotic disorder characterized by abnormalities in the perception or expression of reality. "PRSS16, or serine protease 16, plays an important role in human life processes and has been identified as a risk gene for schizophrenia." (PMID 41438618, 2025).
thymoma (3 papers, 2020 to 2023). A neoplasm arising from the epithelial cells of the thymus. "PRSS16-positive epithelial cells were scattered in B1 thymoma, and a network of PRSS16-positive epithelial cells was seen in B2 and B3 thymoma, which was consistent with the morphology of type B thymomas." (PMID 36797681, 2023). "The expression of β5t, PRSS16, and cathepsin V was higher in type AB and B thymomas than in MNT (p < 0.05)." (PMID 36797681, 2023). "Moreover, the expression of β5t and PRSS16 has significantly increased in type AB thymomas as compared with type A thymomas (p < 0.05)." (PMID 36797681, 2023). "Moreover, our results indicated that A and AB thymomas could compose of spindle cells, the application of β5t and PRSS16 helped to identify type AB and A thymomas." (PMID 36797681, 2023). "CNOT2, CNOT9, CD99, PRSS16, PSMB11, and SHMT1 were found with high abundance in thymoma and participated mainly in nucleic acid and amino acid metabolism." (PMID 31967407, 2020). "Recently, WHO had suggested a dozen of histochemical markers to differentiate type A and type B thymoma, including TdT, CD1a, CD99, PSMB11 (Beta5T), PRSS16, Cathepsin V, and desmin." (PMID 31967407, 2020). "Compared with conventional subtyping markers (e.g., TdT, PRSS16, and PSMB11), CNOT2/9 and SHMT1 not only exhibited good segregating capabilities for thymoma and TSCC, but also showed great prognosis indicating potentials." (PMID 31967407, 2020). "In this study, we aimed to explore the expression of thymic cortical epithelial markers (β5t, PRSS16, and cathepsin V) and medullary epithelial markers (claudin-4, CD40, and AIRE) in thymoma and TSCC and its correlation with histological classification, staging, and prognosis." (PMID 36797681, 2023). "Our results found that for cortical epithelial markers the expression of β5t, PRSS16, and cathepsin V was higher in type AB and B thymomas than in micronodular thymoma with lymphoid stroma (MNT), and we observed a dramatic increase of β5t and PRSS16 expression in type AB compared to type A thymomas." (PMID 36797681, 2023). "Interestingly, another cortical epithelial cell marker in thymoma, PRSS16, showed no significantly different expression between type B (cortical) and type A (medullary) in our proteomic survey." (PMID 31967407, 2020). "PRSS16 was expressed in 78.3% (18/23) of type B, and 61.5% (8/13) of type AB thymoma, not in MNT and type A thymoma, and rarely expressed in TSCC (28.6%, 2/7)." (PMID 36797681, 2023).
Autoimmunity (2 papers, 2004 to 2011). The occurrence of an immune reaction against the organism's own cells or tissues. "Prss16 encodes a thymus specific protease which is specifically expressed by epithelial cells in the thymic cortex and plays a role in T-cell development and, perhaps, in susceptibility to autoimmunity." (PMID 15504237, 2004). "PRSS16 is a serine protease involved in autoimmunity and the presentation of self-antigens within the thymus." (PMID 22567321, 2011).
depression (2 papers, 2020 to 2022). "These colocalization sites included eQTLs for YPEL3, which is highly expressed in whole blood and affects neural development, as well as PRSS16, which impacts immunologic development and has been implicated in multiple GWAS for depression phenotypes." (PMID 32600345, 2020).
diabetes (2 papers, 2002 to 2019). "ALGA0039405 is located in PRSS16, which acts in T-cell development and antigen-presenting pathways and is associated with human diabetes susceptibility." (PMID 31316547, 2019). "Recently, the gene ecoding Prss16 has been linked to insulin dependent diabetes mellitus (IDDM) susceptibility independent of HLA-DR3 suggesting the Prss16 may be involved in the development of autoimmune disease." (PMID 15144014, 2002).
acute appendicitis (1 paper, 2025). "Furthermore, we found that MDD and acute appendicitis have three shared genes: PRSS16, ZNF602P, and ZNF204P." (PMID 41438618, 2025). "And we found that five genes C4A, FLOT1, LINC00243, MICB, and PRSS16 shared the same tissues between MDD and acute appendicitis." (PMID 41438618, 2025). "Finally, we defined three shared genes: PRSS16, ZNF602P, and ZNF204P by TWAS and nine pleiotropic genes C4A, FLOT1, LINC00243, MICB, and PRSS16 by colocalization analysis between MDD and acute appendicitis." (PMID 41438618, 2025). "Finally, the colocalization analysis identified five shared pleiotropic genes for MDD and acute appendicitis: C4A, FLOT1, LINC00243, MICB, and PRSS16." (PMID 41438618, 2025). "Additionally, through the colocalization analysis, we identified five shared pleiotropic genes between MDD and acute appendicitis: C4A, FLOT1, LINC00243, MICB, and PRSS16." (PMID 41438618, 2025).
ovarian carcinoma (1 paper, 2019). A malignant neoplasm originating from the surface ovarian epithelium. "There were two downregulated transcription factors (BARX2 and CDX2), a glutathione regulating enzyme (GGT6) and a serine protease that correlates with improved survival in ovarian cancer (PRSS16)." (PMID 31052165, 2019).
sarcoidosis (1 paper, 2025). Sarcoidosis is a multisystemic disorder of unknown cause characterized by the formation of immune granulomas in involved organs. "Among them, there were 14 genes (ABT1, BTN2A2, C2orf74, CCDC88B, FAM213A, MDH2, METTL21B, PRSS16, RP3-473L9.4, TCF19, TSFM, UBASH3A, UQCC2, ZSCAN26) associated with sarcoidosis risk consistently across these tissues." (PMID 40075078, 2025). "In addition, our TWAS pinpointed many tissue-specific sarcoidosis-associated genes and found expressions of 14 genes (ABT1, BTN2A2, C2orf74, CCDC88B, FAM213A, MDH2, METTL21B, PRSS16, RP3-473L9.4, TCF19, TSFM, UBASH3A, UQCC2, ZSCAN26) associated with sarcoidosis across all three target tissues." (PMID 40075078, 2025).
thymic epithelial tumors (1 paper, 2023). "Our results demonstrated that thymic cortical and medullary epithelial markers including β5t, PRSS16, cathepsin V, and AIRE could be used as ancillary markers in the diagnosis and prognosis of thymic epithelial tumors." (PMID 36797681, 2023).
thymic tumors (1 paper, 2023). "In conclusion, our findings, for the first time, estimated the expression of thymic cortical (β5t, PRSS16, and cathepsin V) and medullary epithelial markers (AIRE, CD40, and claudin-4) in differential diagnosis, Masaoka-Koga stage, histological classification, and prognosis of thymic tumors." (PMID 36797681, 2023).
tumor (2 papers, 2022 to 2024). "Among the core genes, PRSS16, encoding a thymus-specific serine protease (TSSP), which is involved in CD4+ T-cell maturation in the thymus, has tumor suppressor activity." (PMID 39600695, 2024).
cancer (1 paper, 2024). A tumor composed of atypical neoplastic, often pleomorphic cells that invade other tissues. "Consequently, we conducted a pan-cancer analysis of gene promoter methylation and observed significant associations between several genes, including ZNF323, ZSCAN23, SCAND3, PRSS16, ZNF391, NKAPL, and ZNF311, and promoter methylation." (PMID 38495498, 2024).
PRSS16 also shares sentences with these, for which no sentence is quoted: gout (2 papers); infection (2); autoimmune disease (1); colitis (1); psychiatric diseases (1); Stroke (1); trichinellosis (1).